RNU6-338P (RNA, U6 small nuclear 338, pseudogene)
Gene: Small nuclear RNA gene on chromosome 22 (31,388,733 to 31,388,837, reverse strand). Ensembl gene ENSG00000206615.
Homologues: Orthologues: chimpanzee U6 (100% identical), dog U6 (92% identical), pig U6 (92% identical), rat LOC120103210 (86% identical), mouse Gm56093 (78% identical). Paralogues in human: RNU6-1124P (95% identical), RNU6-1011P (93% identical), RNU6-12P (93% identical), RNU6-13P (93% identical), RNU6-140P (93% identical), RNU6-25P (93% identical), RNU6-29P (93% identical), RNU6-32P (93% identical), RNU6-33P (93% identical), RNU6-38P (93% identical), RNU6-41P (93% identical), RNU6-49P (93% identical), and 1288 more.